HRAS (HRas proto-oncogene, GTPase)
Diseases named in the same sentence as HRAS in open-access papers (continued):
Sharing a sentence is not in itself a finding about the gene and the disease.
thymoma (13 papers, 2017 to 2026). A neoplasm arising from the epithelial cells of the thymus. "HRAS mutations have been reported to be prevalent in Type A and AB thymomas, being the second most mutated gene in these tumors with a frequency of 7%." (PMID 38338833, 2024). "Notably, NRAS mutations predominantly manifest in thymic carcinoma, whereas HRAS mutations are more prevalent in thymoma cases." (PMID 37849766, 2023). "Three (17 %) of the 18 type A thymomas harbored a non-synonymous mutation in the HRAS oncogene." (PMID 27844328, 2017). "HRAS was the only mutated gene in type A thymomas in this study." (PMID 27844328, 2017). "One thymic carcinoma harbored a NRAS and three type A thymomas a HRAS mutation." (PMID 27844328, 2017). "In these studies, GTF2I mutation was accompanied with HRAS and NRAS mutations, suggesting a potential exclusivity to indolent thymomas." (PMID 38338833, 2024). "In the TCGA-THYM database, the most common somatic mutations in thymomas also included the genes GFT2I (50%) and HRAS (8%), as well as the genes TTN and MUC16, each with 7%." (PMID 38338833, 2024). "For patients with types A and B1/B2 thymoma (n = 9), seven gene mutations, including MTOR, BRCA1, APC, NF1, HRAS, NTRK3, and PTCH1, were detected, and each gene appeared only once in patients with non-TCs+type B3 TETs." (PMID 34307137, 2021). "Finally, Subtype 4 includes both type A and type AB thymomas and displays a relatively higher incidence of somatic mutations in GTF2I and HRAS." (PMID 37849766, 2023). "In The Cancer Genome Atlas study of 117 early-stage, resected thymic tumor specimens, molecular hallmarks of thymomas, which accounted for the majority of cases of this study, also included GTF2I mutations, specific for type A, and mutations in HRAS and NRAS mutations." (PMID 35749302, 2022). "Significant enrichment of mutated genes of the RAS and PI3K-Akt signalling pathways was reported in thymomas (AKT3, ALK, CSF1R, FGFR4, KRAS, NRAS, HRAS, PIK3CA), and their role in thymoma development was suggested." (PMID 35884448, 2022). "Gene mutations previously reported in type A and AB thymoma (e.g., GTF2I, HRAS, KRAS) were not identified in our cohort." (PMID 41344988, 2026).
follicular thyroid carcinoma (12 papers, 2011 to 2026). "We report hormone-producing lung and bone metastases from an HRAS-mutated high-grade differentiated thyroid carcinoma (HGDTC) originating from follicular thyroid carcinoma (FTC), with a brief literature review." (PMID 41993975, 2026). "It has been shown that mutations in the RAS family genes (NRAS, KRAS, HRAS) are most commonly associated with follicular thyroid carcinoma (FTC), but they are also present in three other types, including anaplastic thyroid cancer (ATC)." (PMID 39767735, 2024). "In comparison, BRAF p.V600E occurs in over 50% of adult papillary thyroid carcinoma (PTC) and NRAS/HRAS/KRAS mutations in 30-45% of follicular thyroid cancer and follicular variant PTC." (PMID 39558957, 2024). "In 2 cases of follicular thyroid carcinomas with molecular changes, 1 patient carried both HRAS and TERT mutations, and 1 patient carried TERT mutation." (PMID 36737779, 2023). "Gene alterations in follicular thyroid carcinoma include point mutations in HRAS, NRAS, and KRAS genes." (PMID 36607876, 2023). "RAS (including KRAS, NRAS, and HRAS) molecular alterations are most frequently seen in follicular carcinomas and benign adenomas." (PMID 39456540, 2024). "NRAS, HRAS, and KRAS mutations, which are seen in 30–50% of follicular thyroid cancer (FTC), were detected in 8% of classic and in 33% of follicular variant PTCs." (PMID 34630336, 2021).
thyroid nodule (12 papers, 2019 to 2026). A small circumscribed mass in the THYROID GLAND that can be of neoplastic growth or non-neoplastic abnormality. "Thyroid nodules with CNAs alone or in conjunction with lower risk mutations such as HRAS, NRAS, DICER1, EIF1AX, and GEA are more likely to be low-risk neoplasms." (PMID 36551633, 2022). "In indeterminate thyroid nodules, NRAS mutations are typically the most frequent, followed by KRAS and HRAS." (PMID 40748901, 2025). "In a study that demonstrated the variety in the molecular profile of 96 surgically resected thyroid nodules, RAS (HRAS, NRAS, KRAS) oncogene mutations were present, either alone or with other mutations in almost one-half of cases (46 of 96 cases; 48%)." (PMID 37175943, 2023). "Thyroid nodules with GEA and low-risk mutations such as HRAS or NRAS are significantly more likely to be low-grade malignancies such as a follicular variant of papillary thyroid carcinoma." (PMID 36612045, 2022). "Mutations in RAS proto-oncogenes (NRAS, HRAS, KRAS) are common in thyroid nodules, though their prognostic significance remains unclear." (PMID 41784850, 2026). "The RAS genes family (NRAS, HRAS, and KRAS) mutations represent the majority (about 70%) of all mutated cases, especially in indeterminate cytology, and they can be seen in histologically benign and malignant thyroid nodules." (PMID 38884926, 2024). "Furthermore, molecular analysis using the following markers (BRAF V600E, NRAS, HRAS, KRAS, RET/PTC, and PAX8/PPARg) to evaluate preoperative genetic mutations and rearrangements has been shown to have significant diagnostic value in thyroid nodules with indeterminate cytology." (PMID 37732121, 2023). "In thyroid nodules with no aggressive features, GEA was most commonly associated with the HRAS mutation (n = 12, 34.3%), NRAS mutation (n = 10, 28.6%), and CNA (n = 8, 22.8%)." (PMID 36612045, 2022).
cutaneous melanoma (11 papers, 2005 to 2025). A primary melanoma arising from atypical melanocytes in the skin. "NRAS mutations occur in ∼20% of human cutaneous melanomas, while HRAS and KRAS mutations are rare in this disease." (PMID 28497782, 2017). "There is only one recent paper mentioning the occurrence of HRAS mutations in upto 10% (2/20 cases examined) of primary cutaneous melanomas." (PMID 25593912, 2014). "In this study, we assessed germline variants of HRAS in the context of cutaneous melanoma; rs12628 was frequently observed and considered an informative SNP." (PMID 22618666, 2012). "This is consistent to current literature that BRAF, HRAS, KRAS or KIT mutations occur rarely in meningeal MCs and are more commonly observed in cutaneous melanoma." (PMID 41324772, 2025). "This study highlighted a novel role for the prognostic value of HRAS mRNA expression in cutaneous melanoma." (PMID 29349077, 2017). "Few studies have focused on the transcriptional level of RAS isoforms (KRAS, NRAS, and HRAS) in cutaneous melanoma." (PMID 29349077, 2017). "We also found that there were 206 genes that negatively correlated with HRAS expression significantly overlapped with genes positively correlated with KRAS/NRAS in cutaneous melanoma." (PMID 29349077, 2017). "More mechanistic studies are needed to further elucidate the relationship between HRAS mRNA and the prognosis of cutaneous melanoma." (PMID 29349077, 2017). "In our study, we found that HRAS mRNA level was correlated with the poor prognosis of the cutaneous melanoma." (PMID 29349077, 2017). "This study aimed to investigate the prognostic value of HRAS mRNA expression in cutaneous melanoma." (PMID 29349077, 2017). "Our data indicated that HRAS mRNA expression, but not KRAS or NRAS, was correlated with prognosis in cutaneous melanoma." (PMID 29349077, 2017). "Furthermore, Because LCK was the most important prognostic factor in cutaneous melanoma, the negative correlation between HRAS and LCK at transcriptional level indicates that HRAS might be a critical molecule in cutaneous melanoma." (PMID 29349077, 2017).
hepatocellular carcinoma (10 papers, 2015 to 2024). A malignant tumor that arises from hepatocytes. "HRAS promotes hepatocellular carcinoma progression by upregulating HSPB1, reducing ferroptosis, and enhancing cell proliferation and invasion." (PMID 39315094, 2024). "In order to evaluate the expression level of hub genes (HRAS, SLC7A11 and SLC2A1) in hepatocellular carcinoma, we conducted immunohistochemical (IHC) analysis." (PMID 37051544, 2023). "Liu demonstrated in hepatocellular carcinoma cell lines that nEGFR can affect cell apoptosis by stimulating the expression of SOS1, which then activates the HRAS/PI3K/AKT pathway, leading to nuclear translocation of p-AKT and Bcl-2." (PMID 36982894, 2023). "At present, limited studies on PIK3CD, HRAS, E2F2, BIGF1, WNT4, and VAV3 genes have been reported in hepatoma cells, indicating the need for further research." (PMID 33959508, 2021). "Finally, the activation of the HRAS/PI3K/AKT pathway by EGFR-induced SOS1 also inhibits cisplatin-induced apoptosis, suggesting a common apoptosis-evasion mechanism in hepatoma cells." (PMID 25980493, 2015).
papilloma (10 papers, 2014 to 2025). A benign epithelial neoplasm that projects above the surrounding epithelial surface and consists of villous or arborescent outgrowths of fibrovascular stroma. "Only the oncogenic hotspot mutations in HRAS (83%) were present in nearly all cases of papilloma, whereas alterations in cell cycle genes and chromatin modifying genes were rarely observed, suggesting that papilloma was driven primarily by RAS pathway activation (Fisher’s exact test, p = 5.0E-5)." (PMID 37704624, 2023). "The result showed that papilloma carried higher mutation rate of genes, such as MPRIP, HRAS, and MAP3K1, while PUC carried a higher mutation rate of genes, such as FGFR3 and PPFIBP1 (Fisher’s exact test, p < 0.05)." (PMID 37704624, 2023). "The result showed that patients with HRAS mutations have higher levels of HRAS protein expression (Wilcoxon rank-sum, p = 0.002), and the expression of HRAS in papilloma was higher than PUC (Wilcoxon rank-sum, p = 2.1E-4)." (PMID 37704624, 2023). "We also investigated the protein expression level of these mutations, the results showed four proteins (HRAS, ALDH7A1, CBLB, and MPRIP) were differently expressed between papilloma and PUC." (PMID 37704624, 2023). "We further found that higher expression of HRAS was positively correlated with higher phosphorylation of MAP3K1, MAPK1, and RPS6KA3, and the expression of RPS6KA3 was higher in papilloma than PUC." (PMID 37704624, 2023).
salivary gland cancer (10 papers, 2015 to 2025). A primary or metastatic malignant neoplasm that affects the major or minor salivary glands. "In this study, we evaluated the frequency of HRAS mutations in HNCs, including salivary gland carcinomas, and we revealed the clinical characteristics of HRAS mutation-positive cancers." (PMID 40243851, 2025). "Distant metastasis at diagnosis was observed in only one case of salivary gland carcinoma with an HRAS mutation." (PMID 40243851, 2025). "HRAS mutations of salivary gland carcinomas are detected in mucoepidermoid carcinomas and salivary duct carcinomas with an incidence of 14% of cases at our institute, which is consistent with previous reports." (PMID 40243851, 2025). "The farnesyltransferase inhibitor tipifarnib showed 58% stable disease as the best response in HRAS mutated patients with salivary gland carcinoma cohort which comprised 8% MECs." (PMID 36612247, 2022). "Although HRAS mutations are negligible in human cancers, salivary gland carcinoma, mouth carcinoma, and vulva carcinoma possess relatively high rates of HRAS mutation." (PMID 34301278, 2021). "We have also shown that salivary gland carcinomas with HRAS mutations have poorer OS." (PMID 40243851, 2025). "HRAS mutations were found in 14% of salivary gland carcinomas." (PMID 40243851, 2025). "However, HRAS mutations in salivary gland carcinomas are not limited to epithelial myoepithelial carcinomas." (PMID 40243851, 2025). "In addition, tipifarnib also resulted in modest clinical activity in HRAS‐mutant salivary gland cancer and urothelial carcinoma harboring HRAS mutations." (PMID 36254250, 2022). "The fact that HRAS mutations are more prevalent in salivary gland carcinomas compared to HNSCCs, and are likely associated with poorer prognosis, suggests that HRAS-targeted therapy such as tipifarnib may hold significant promise not only for HNSCCs but also for salivary gland carcinomas." (PMID 40243851, 2025). "The farnesyltransferase inhibitor trials were initiated based, in part, on HRAS-mutant mammary and salivary carcinoma mouse models, where it was determined that if HRAS is not farnesylated, it cannot be properly localized to the plasma membrane and therefore cannot signal." (PMID 38800401, 2024).
thyroid tumor (10 papers, 2015 to 2025). A benign or malignant neoplasm affecting the thyroid gland. "Human thyroid tumors are often characterized by activating point mutations in BRAF, NRAS, HRAS, or KRAS, leading to the overactivation of MAPK- and mTOR-signaling pathways." (PMID 40711277, 2025). "In this study, we introduce subcellular localization, an erstwhile unconsidered factor, as a determinant of the dissemination potential of thyroid tumors driven by either HRAS or NRAS oncoproteins." (PMID 32927904, 2020). "It was of interest to unravel the mechanism whereby HRAS regulates the antagonistic behavior of thyroid tumor cells with respect to their growth and dissemination capabilities." (PMID 32927904, 2020). "Overall, these results demonstrate that HRAS controls the growth and dissemination of thyroid tumors through an autocrine regulatory loop mediated by VEGF-B." (PMID 32927904, 2020). "In summary, we demonstrate that HRAS-driven thyroid tumors potential for dissemination is highly dependent on the sublocalization from which HRAS signals emanate according to a mechanism mediated by VEGF-B secretion." (PMID 32927904, 2020). "We show that alterations in APT-1 expression levels can dramatically affect the behavior of thyroid tumors, based on its role as a regulator of HRAS sublocalization at distinct plasma membrane microdomains." (PMID 32927904, 2020). "As such, our results unveil APT-1 as a potential marker of the aggressiveness of HRAS mutant thyroid tumors." (PMID 32927904, 2020). "Overall, contrarily to the prevailing concept that bigger tumors are more prone to metastasize, we herein demonstrate that HRAS/NRAS-driven thyroid tumors exhibit the opposite behavior." (PMID 32927904, 2020). "In contrast, in human medicine, the molecular characterization of thyroid tumor-ascertained mutations in BRAF, NRAS, HRAS, and KRAS is relevant as they are players implicated in thyroid tumor progression through their activation of MAPK- and mTOR-signaling pathways." (PMID 40711277, 2025). "Moreover, we have identified the acyl protein thioesterase APT-1, a regulator of HRAS sublocalization, as a determinant of thyroid tumor growth versus dissemination." (PMID 32927904, 2020). "HRAS and BRAFV600E mutations (unlike other genetic modifications) exhibit less response to histone deacetylase (HDAC) inhibitor therapies regardless of thyroid tumour subtypes." (PMID 39558949, 2024). "There are 3 isoforms of RAS: HRAS, KRAS and NRAS found in thyroid tumours." (PMID 27703585, 2016). "Interestingly, the authors reported this feature specifically in murine thyroid tumors driven by BRAFV600E mutation, but not in those driven by HRAS mutation." (PMID 31906302, 2020).
bladder tumors (9 papers, 1998 to 2023). "Though mutations in HRAS in urinary bladder tumors have been linked with increased Ras expression, their frequency is low (5%)." (PMID 27713144, 2016). "Concurrent mutations in the coding and regulatory regions of HRAS in urinary bladder tumors are associated with increased Ras expression, and constitutively active HRAS triggers bladder carcinogenesis in mouse urothelium." (PMID 27713144, 2016). "HRAS mutations are less common, but they have a high prevalence in skin papillomas and urinary bladder tumors." (PMID 21931711, 2011). "This corroborates our previous study, which showed that bladder tumour cell lines containing mutant RAS were intrinsically resistant to FGFR inhibition and a recent finding of resistance due to overexpressed wild type HRAS in FGFR‐dependent cell lines, including RT112." (PMID 36385700, 2023).
epithelial-myoepithelial carcinoma (9 papers, 2015 to 2025). A malignant neoplasm which occurs mostly in the major salivary glands (most frequently in the parotid gland), but also in the minor salivary glands of the oral mucosa and the tracheobronchial tree. "Of those, SSX2 and SS18 have been identified in histology-type investigations in the literature, whilst MVP2 function is little known, while HRAS is implicated in various types of cancers (i.e., salivary duct carcinoma, epithelial myoepithelial carcinoma, etc." (PMID 34359782, 2021). "In doubtful cases, it seems that HRAS mutation testing is context-specific for epithelial-myoepithelial carcinoma." (PMID 32193604, 2020). "Additionally, EWSR1-ATF1 rearrangements have been found in HCCC, and HRAS exon three mutations are seen in most cases of epithelial-myoepithelial carcinoma." (PMID 39958930, 2025). "Additional mutations in PIK3CA also affected particularly epithelial-myoepithelial carcinomas and salivary duct carcinomas, occurring simultaneously with HRAS mutations in almost all cases, pointing to an unknown and therapeutically relevant molecular constellation." (PMID 26053092, 2015). "HRAS mutations accounted for more than 90% of RAS mutations, occurring especially in epithelial-myoepithelial carcinomas and salivary duct carcinomas." (PMID 26053092, 2015).
leukemia (9 papers, 2012 to 2023). A malignant (clonal) hematologic disorder, involving hematopoietic stem cells and characterized by the presence of primitive or atypical myeloid or lymphoid cells in the bone marrow and the blood. "It is not clear whether HRAS mutations outside these hotspots are non-functional passenger mutations or rare activating mutations which have been identified e.g. for N- and KRAS in leukemia." (PMID 26544513, 2015).